TNF (tumor necrosis factor)
Diseases named in the same sentence as TNF in open-access papers (continued):
Sharing a sentence is not in itself a finding about the gene and the disease.
Obesity (continued). "In the current study, the serum levels of TNF-α, CRP, IL-6, IL-12, sVCAM-1 and sICAM-1 were evaluated with the progression of obesity classes I–III." (PMID 32893859, 2020). "Such pro-inflammatory cytokines, tumor necrosis factor (TNF-α) and interleukin-6 (IL-6) are believed to link obesity to T2D through insulin resistance." (PMID 33113859, 2020). "4-HIL reversed obesity-induced increased expression of iRhom2/TACE, and additionally reduced the levels of TNF-α in a dose-dependent manner." (PMID 33298044, 2020). "In all participants with obesity (group 2 and 3), correlations between serum biomarkers (hs-CRP, IL-6, TNF-α, M30 level, insulin resistance) and LV diastolic function parameters were analyzed by multivariate regression." (PMID 31120986, 2019). "The immune cell infiltration of adipose tissue increased production of pro-inflammatory cytokines (e.g., TNF-α, IL-1, IL-6, and IL-8) that were reported to be associated with increased risk of nephritis in HSP, which may be a potential mechanism to explain the relationship between obesity and HSPN." (PMID 31735105, 2019). "In this study, with the reduction of obesity, HFD+SC06 also significantly decreased the concentration of IL-6 and TNF-α compared to that of HFD." (PMID 31191487, 2019). "Inflammatory cytokines, tumor necrosis factor-alpha (TNF-α) and interleukin-6 (IL-6) are all recognized as components of the inflammatory mechanisms accompanying the status of obesity and MetS." (PMID 31550292, 2019). "Obesity positively regulates osteoclasts functioning by up-regulating the production of RANKL, LIGHT, TRAIL, TNFα, MCP1 and inhibiting osteoblastogenesis, thereby accelerating bone resorption." (PMID 31130918, 2019). "The activity of IDO is stimulated by proinflammatory cytokines, which are elevated in obesity: interleukin-2 (IL-2), interferon-γ (IFN-γ), and tumor necrosis factor-alpha (TNF-α)." (PMID 31906073, 2019). "In adipose tissues in obesity, expressions of pro-inflammatory cytokines such as MCP-1, IL-6, TNFα, and IL-1β in macrophages and/or adipocytes have been reported to increase." (PMID 31509948, 2019). "In similar studies, exposure to high fat diet during lactation (only) induced an early-onset obesity in offspring (C57BL/N mice) at 3 weeks of age, with increased expression of mRNAs of IL-5, IL-13, IL-17A and TNFα in the lung." (PMID 30700289, 2019). "Obesity can result from the reduced lipolytic effect of insulin in PCOS, in turn, by increased serum inflammatory mediators such as TNFα and high-sensitivity CRP (hs-CRP), leads to beta cell dysfunction and insulin resistance of PCOS." (PMID 32133054, 2019). "Administration of TNF-α neutralizing antibody to patients with type 2 diabetes does not reduce their insulin resistance, suggesting that the inflammatory process could be a result of obesity, but not a cause of insulin resistance or diabetes." (PMID 31447776, 2019). "The transfection of ss-miR156c mimic was also performed in human type 1 macrophages (M1) and TNF-α-stimulated murine RAW 264.7 cells, since during obesity macrophages recruitment is elicited contributing to inflammation and insulin resistance." (PMID 31453381, 2019). "Resistin could be a link between insulin resistance and obesity; its release reduces peripheral insulin sensitivity, increases endogenous glucose production by the liver, induces insulin resistance, and stimulates proinflammatory cytokines (e.g., IL-6 and tumor necrosis factor (TNF)-α)." (PMID 31671697, 2019). "Osteopontin expression in human macrophages is also upregulated by a variety of pro-inflammatory mediators, including TNF-α, IL-6, and oxidized LDL, known to be elevated in obesity, type 2 diabetes, and cardiovascular disease." (PMID 31694146, 2019). "Of note, it has also been demonstrated the inhibitory effects of sweet cherry anthocyanins on obesity development in HFD fed mice, by slowing down TNFα and IL-6 levels." (PMID 31130968, 2019).
Obesity (continued). "This study was designed to explore the effects of tumor necrosis factor alpha (TNFα) in the PVN on the AAR and SNA in rats with obesity-related hypertension (OH) induced by a high-fat diet for 12 weeks." (PMID 31391086, 2019). "Adipocytokines, such as tumor necrosis factor (TNF)-α, plasminogen activator inhibitor (PAI)-1, monocyte chemoattractant protein (MCP)-1, leptin, and adiponectin, play critical roles in obesity-related diseases." (PMID 31648235, 2019). "Tumor necrosis factor alpha (TNF-α), one of the well-known inflammatory factors, was demonstrated as a potential mediator of the PCOS-related physiological processes such as obesity, insulin resistance, and androgen expression." (PMID 31170164, 2019). "A previous study reported an increased expression of inflammatory markers, including TNFα and MIP1α, in PVAT of middle-aged mice; however, only in those with diet-induced obesity." (PMID 31906225, 2019). "Increased pro-inflammatory cytokines such as TNF-α, IL-1, IL-6, and PGE2 are hallmarks of obesity and obesity-induced breast cancer development." (PMID 31616626, 2019). "Treatment with tumor necrosis factor-α (TNFA), one of the key adipokines in obesity and insulin resistance, increases miR-2725." (PMID 31554889, 2019). "In addition, obesity causes lipid accumulation, activates JNK and NF-κB signaling pathways, and might subsequently increase the production of pro-inflammatory cytokines such as TNF-α and IL-6." (PMID 31866871, 2019). "Higher levels of some adipocytokines (TNF, CCL2/MCP-1) in ScAT from OA than RA patients can also result from different body compositions, as obesity was more frequent in OA than RA group." (PMID 30280295, 2019). "More recently, the long-term assessment of anti-TNF-α inhibitor treatment to individuals diagnosed with metabolic syndrome has been shown to increase adiponectin levels, confirming a role for TNF-α in obesity-related insulin resistance in humans." (PMID 31420057, 2019). "The expression level of the TNF-α gene was positively correlated with the expression level of the RARRES2 gene in the GO in patients with T2DM (with grade I and II obesity) (r = 0.66, p < 0.05 and r = 0.67, p < 0.05, respectively)." (PMID 30871547, 2019). "Within this range of M1 polarity, the adipose tissue (AT-SVF) macrophages had the lowest TNF-α/IL-10 ratios, and switched their cytokine response to LPS to a more pro-inflammatory profile in HFD-induced obesity." (PMID 31316525, 2019). "This suggests that TNF-α is a more prominent biomarker of obesity-induced inflammation than 1L-8 and MCP-1, in particular for this population, with high levels of obesity." (PMID 31159253, 2019). "In the obese state, necrotic adipocyte recruits macrophages to secret pro-inflammatory cytokines, such as TNF-α, IL-1β, IL-6, MCP-1, which potentially arouses obesity-related insulin resistance." (PMID 31548850, 2019). "Recent evidence suggests that tumor necrosis factor α (TNFα) induces TBK1 and IKKε, which play pivotal roles as mediators of obesity-induced systemic low-grade inflammation." (PMID 30791439, 2019). "Exercise induced a decrease in the pro-inflammatory cytokines, such as tumor necrosis factor α (TNF-α) and IL-6, C-reactive protein (CRP), thereby assisting the prevention or mitigation of such chronic-degenerative diseases such as obesity and diabetes." (PMID 30666216, 2018). "As noted in the obesity section, increased BMI or obesity is related to greater systemic inflammation (e.g., CRP, IL-6, and TNF-α levels)." (PMID 30538987, 2018). "HSP72 downregulates expression of TNFα, JNK and IKK, thereby alleviating metabolic dysregulation in obesity-induced insulin resistance." (PMID 29233861, 2018). "An anti-inflammatory effect of apigenin was previously reported in a murine model of HFD-induced obesity, where its administration reduced plasma levels of MCP-1, TNF and IL-6." (PMID 29641549, 2018).
Obesity (continued). "In obesity, the hypertrophied adipocytes produce proinflammatory cytokines including MCP-1, TNF-α and IL-6." (PMID 29473848, 2018). "Interestingly, other inflammatory markers, such as interleukin-15 (IL-15), tumour necrosis factor alpha (TNF-α), interferon gamma-induced protein 10 (IP-10), interleukin 6 (IL-6), and interleukin 8 (IL-8), correlated only with the microbiota profiles from children developing obesity." (PMID 30534614, 2018). "Similarly, using a network-based pharmacological analysis, mulberry extracts have been proposed to regulate TNF-α, PPARγ, glycogen synthase kinase-3 beta (GSK3B), insulin receptor substrate 1 (IRS1), interleukin 6 (IL-6) and other proteins involved in diabetes and obesity associated complications." (PMID 30577684, 2018). "It was proposed by Frasca and Blomberg that increased hypoxia and CCL-2 expression, along with increased adipocyte-derived TNF-α, IFN-γ, IL-6, and IL-21, prompted an obesity-driven accumulation of pro-inflammatory B-cells, which is exacerbated with ageing." (PMID 29479350, 2018). "Low grade inflammation plays a role in the development of obesity and metabolic disorders and in a recent report, elevated serum levels of CRP and TNF-α in 300,000 μkd DEHP in utero exposed offspring were detected." (PMID 30519216, 2018). "Maternal overnutrition in a sheep model of obesity demonstrated that inflammatory markers such as CD-68, TGF-β1, and TNF-α found in the mother are also identified in the offspring after birth." (PMID 30027100, 2018). "With the development of obesity, adipocytes can release proinflammatory mediators, such as CC chemokine ligand (CCL)-2 (also known as MCP-1), tumor necrosis factor (TNF)-α, free fatty acids (FFAs), which recruit M1 macrophage." (PMID 29415997, 2018). "Taken together, TNFα-activated IKK and JNK signaling are increased in the liver upon obesity, thereby revealing their dysregulation and combined oncogenic potential in obese patients." (PMID 30591653, 2018). "Hypertrophic adipocytes can secrete various pro-inflammatory cytokines such as TNF-α and IL-6, and the level of pro-inflammatory factor MCP-1 is believed to be significantly increased during the development and progression of obesity." (PMID 30347741, 2018). "Inflammatory marker IL-6, TNF-alpha and MCP-1 levels in fasting plasma were similar between GNB3-T/+ and WT mice prior to and during obesity." (PMID 29206867, 2017). "The main mechanism of Ephedra sinica's ability to reduce obesity and hyperglycemia involves increasing peroxisome proliferator-activated receptor alpha (PPAR-α) and adiponectin activity and reducing tumor necrosis factor-alpha (TNF-α) activity." (PMID 29234439, 2017). "Inflammatory cytokines, such as tumor necrosis factor-α (TNF-α) and interleukin-6 (IL-6), are individually considered as important contributors to endothelial dysfunction in obesity and type 2 diabetes (T2D)." (PMID 29095915, 2017). "Similar to TNFα expression, DUSP5, an ERK1/2 specific phosphatase, increased with the development of obesity." (PMID 29018280, 2017). "Inflammatory factors such as TNF-α, IL-6, IL-1β, monocyte chemoattractant protein-1 (MCP1), and macrophage recruitment are also increased in obesity; these factors negatively affect adipocyte metabolism and its lipid storage capacity." (PMID 28607631, 2017). "Since the adipocytes produce adipokines, the increase of TNF-α, resistin, and visfatin was found under obese conditions in mice, which melatonin could suppress to some degree when used at 100 mg/kg, indicating the beneficial impact of melatonin to control obesity." (PMID 28387721, 2017). "Increased TNF-α upregulates MCP1 expression and leads to adipose tissue macrophage infiltration in obesity." (PMID 28607631, 2017). "On the other hand, maternal obesity compounded with the Mc4r KO genotype had decreased α-SMA (−0.73-fold, p < 0.01), TNF-α (−0.54-fold, p < 0.05), and IL6 (−0.56-fold, p < 0.05) hepatic mRNA levels in the offspring." (PMID 28930194, 2017).
Obesity (continued). "Obesity for donor is also related to CD4+ T cell–mediated aGVHD of recipients by controlling the differentiation of CD4+IL-2+, CD4+IFN-γ+ and CD4+TNF-α+ and Th17 cells." (PMID 29088831, 2017). "Recent studies showed that innate lymphoid cell 3-induced IL-17 production was related to obesity-associated AHR through macrophage-derived IL-1β and that blockade of TNF-α attenuated ozone-induced neutrophilic inflammation and AHR in obesity." (PMID 28365872, 2017). "In obesity, increased blood levels of free fatty acids (FFA), tumor necrosis factor alpha (TNF-alpha) and leptin have been demonstrated to contribute to the development of type 2 diabetes." (PMID 29209160, 2017). "It has been reported that ROS generation in contracting skeletal muscle is elevated when there is TNF-α overproduction in the lung and that this can induce muscle dysfunction as observed in COPD and obesity." (PMID 28335527, 2017). "Obesity induces a switch from anti-inflammatory M2 ATM towards pro-inflammatory M1 ATM which secrete pro-inflammatory cytokines, such as TNF-α, IL-6, IL1-β, IL-12, IL-23, and leukocyte-attracting chemokines, such as IL-8, Rantes, MIP-1α and MIP-1β." (PMID 28708082, 2017). "During obesity, leukocyte infiltration in WAT, composed mainly by macrophages, enhances TNF-α and IL-6 production, to initiate and maintain the inflammatory process." (PMID 29220408, 2017). "Specific disruption of the gene expressions of TNFα downstream signals TNFSF11A or NDUFAB1 in the MBH of diet-induced obese mice reverses mitochondrial elongation and reduces obesity." (PMID 28489068, 2017). "CD14+CD16+ monocytes are potent secretors of IL-1, IL-6 and TNF-α, and expanded CD14+CD16+ monocyte populations are found in inflammatory disease states including atherosclerosis, obesity and rheumatoid arthritis." (PMID 28494757, 2017). "Cross-sectional studies have shown that many individuals with obesity and/or MDD have elevated levels of cytokines, including interleukin (IL)-6, tumor necrosis factor (TNF)-α and C-reactive protein (CRP)." (PMID 29176959, 2017). "The significance of TNF-α in the pathology of obesity-induced metabolic dysfunctions has been further demonstrated in genetic and HFD-induced rodent models of obesity wherein TNF-α knockout or neutralization attenuated the development of systemic IR." (PMID 29186929, 2017). "Many studies have shown that pro-inflammatory mediators including tumor necrosis factor-α (TNF-α), interleukin-1β (IL-1β) and interleukin-6 (IL-6) are increased during obesity and diabetes." (PMID 28282929, 2017). "The levels of inflammatory cytokines, like interleukin-6 (IL-6) and tumor necrosis factor-alpha (TNF-α), as well as C-reactive protein (CRP) are elevated in obesity and insulin-resistant states." (PMID 28836404, 2017). "However, on the stage of extremely obesity or diabetes, dysfunctional adipocytes could increase the pro‐inflammatory factors secretion, such as TNF‐α and IL‐6 that modulate an angiogenesis response in adipose tissue 43, 44 and could be a primary contributor of angiogenesis." (PMID 28631352, 2017). "Since IL-15 is induced by inflammatory stimuli, and several inflammatory cytokines such as IL-6, TNFα, IFNγ are implicated in promoting obesity and insulin resistance, we postulated that IL-15 might contribute to the pathogenesis of obesity rather than conferring protection against it." (PMID 27684068, 2016). "In line with the observations of low dose TNFα administration, deletion of TNF receptor 1 (TNFR1), a main TNFα receptor, were protective against diet induced obesity by increasing BAT activation and enhancing thermogenesis." (PMID 26903879, 2016). "Obesity positively regulates osteoclasts functioning by upregulating the synthesis of RANKL, TNF-α, MCP1, IL-6, PTH and M-CSF while also downregulating ERα expression, thereby accelerating bone resorption." (PMID 27746742, 2016).
Obesity (continued). "Chemical messengers (e.g., TNF-α, IL-6, AGE, leptins) that are upregulated or downregulated as a result of obesity have been shown to act as negative regulators of osteoblasts, osteocytes and muscles, as well as positive regulators of osteoclasts." (PMID 27746742, 2016). "In contrast, overexpression of AQP7 improved insulin resistance in dexamethasone and TNFα-treated adipocytes and polyphenol-induced increase in AQP7 expression led to the inhibition of adipocyte hypertrophy in diet-induced obesity in rats." (PMID 27763558, 2016). "Among inflammatory biomarkers, the role of classic inflammatory mediators including tumor necrosis factor α (TNF-α) and C-reactive protein (CRP) have been extensively investigated in obesity." (PMID 26909479, 2016). "In an in vitro model of obesity, 3T3-L1 adipocytes stimulated by LPS and RAW-CM presented increased IL-6 gene expression, as well as TNF-α and IL-6 cytokine production, but decreased peroxisome proliferator-activated receptor (PPAR)γ gene levels." (PMID 27983683, 2016). "In general, proinflammatory plasma markers such as TNF-α, IL-6, and MCP-1 are present in an early inflammatory stage of obesity." (PMID 27869712, 2016). "As expected, TNFα treatment greatly increased MCP-1 secretion, which is consistent with the idea that TNFα is a strong proinflammatory inducer of MCP-1 in obesity." (PMID 28030645, 2016). "Demonstration of elevated expression of transmembrane forms of TNF-α in obesity well confirms the spatial restriction of TNF-α, suggesting the action of this cytokine is restricted to AT because of TNF-α retention on the cell surface." (PMID 26339623, 2015). "Our observations provide an understanding into the complex mechanisms, including changes in Akt, TNFα, IL6 and MCP1 by which estrogen regulates obesity and insulin resistance." (PMID 26317527, 2015). "Early studies in rodent models of obesity and T2DM suggested that increased secretion of tumor necrosis factor alpha (TNFα) from adipose tissue induces insulin resistance relating WAT inflammation and insulin resistance." (PMID 25624106, 2015). "TNF-α, a pro-inflammatory cytokine, is a common component of inflammatory signaling in AD and T2DM and obesity." (PMID 26340637, 2015). "After diet-induced obesity (60% fat diet) in C57BL/6 mice, increased expression in the colon of TNFα was found, which instigated alterations in several components of the Wnt signaling pathway leading to tumor transformation." (PMID 26347815, 2015). "It is well established that circulating pro-inflammatory cytokines [e.g. tumor necrosis factor alpha (TNF-α), interleukin 6 (IL-6)] are induced in obesity and these pro-inflammatory cytokines play a crucial role in the development of metabolic syndrome." (PMID 25861245, 2015). "In 1993, the relationship between obesity and T2DM was described in vivo, when investigators demonstrated that adipose-derived tumour necrosis factor-α (TNF-α) levels in mice were increased during the development of obesity." (PMID 26693205, 2015). "Adipose tissue-derived TNF-α, mainly from ATMs, is a MAP kinase target gene and has been shown to be a major player in obesity-induced insulin resistance and T2D." (PMID 25816341, 2015). "In sharp contrast to elevated TNF-α expression in AT, circulating TNF-α concentrations in obesity are found unchanged or disproportionately increased." (PMID 26339623, 2015). "Finally, as ROS and TNFα, LPS may also act as a major obesity-related inflammatory mediator." (PMID 25685071, 2015). "Obesity promotes a state of chronic low-grade inflammation in WAT mediated by increased plasma concentrations of several adipokines, including TNF-α, IL-6, and C-reactive protein (CRP)." (PMID 26580647, 2015).